DRAM2 (DNA damage regulated autophagy modulator 2)
Diseases named in the same sentence as DRAM2 in open-access papers:
DRAM2 is named in the same sentence as 33 diseases in open-access papers, as found by Europe PMC text mining. Sharing a sentence is not in itself a finding about the gene and the disease. The quoted sentences say what the papers report.
Retinal dystrophy (7 papers, 2017 to 2024). Retinal dystrophy is an abnormality of the retina associated with a hereditary process. "DRAM‐2 has also been implicated in retinal dystrophy and non‐ST segment myocardial infarction (NSTSMI)." (PMID 35060334, 2022). "We found three unrelated patients with a disease-causing DRAM2 variant in a biallelic state from 1555 Japanese individuals of 1314 families with inherited retinal dystrophy." (PMID 32079136, 2020). "Since Dram2 loss causes a slow-progressing and mild retinal dystrophy in mice, we tested if the phenotype could be exacerbated by additional environmental stress." (PMID 37691820, 2023). "However, integration of data from several systems allowed deeper understanding of the pathophysiology of retinal dystrophy associated with DRAM2 loss of function." (PMID 37691820, 2023). "Rare DRAM2 coding variants cause retinal dystrophy with early macular involvement via unknown mechanisms." (PMID 37691820, 2023). "In conclusion, DRAM2-associated retinopathy is a rare inherited retinal dystrophy in Japan." (PMID 32079136, 2020). "The purpose of our study was to use DRAM2 loss as genetic perturbation and compare in vitro human and in vivo mouse models to determine if they could be leveraged to decipher pathophysiologic mechanisms of complex retinal dystrophy." (PMID 37691820, 2023). "Lesion scoring of the damaged areas showed similar severity of retinal dystrophy in Dram2 wt/wt and ko/ko mouse retinas." (PMID 37691820, 2023). "Collectively, our results show that Dram2 loss in mice does not exacerbate retinal dystrophy induced by acute photoreceptor- or RPE-injury, but it exacerbates proliferation of choroidal cells, resulting in more severe choroidal neovascular lesions." (PMID 37691820, 2023). "DRAM2-associated retinopathy is a rare inherited retinal dystrophy, and its outcome has not been determined." (PMID 32079136, 2020). "Thus, DRAM2 made up 0.2% of the inherited retinal dystrophies." (PMID 32079136, 2020). "Of note, DRAM2 cellular function has often been studied in the context of oncogenicity and tumor cell treatment response, and not in the context of neurodegeneration or retinal dystrophy." (PMID 37691820, 2023). "This indicates potential context‐specific effects of the protein in autophagy and that the impact of DRAM‐2 in retinal dystrophy and NSTMI may or may not be autophagy‐dependent." (PMID 35060334, 2022).
cone-rod dystrophy (6 papers, 2020 to 2025). Inherited retinal dystrophies that belong to the group of pigmentary retinopathies. "In DRAM2-associated cone-rod dystrophy, ROs exhibited abnormalities in lipid metabolism, autophagic flux defects, and reduced lysosomal enzyme activity." (PMID 39422807, 2025). "Biallelic mutations in DRAM2 lead to an autosomal recessive cone-rod dystrophy known as CORD21, which typically presents between the third and sixth decades of life." (PMID 38964324, 2024). "To gain insights into the pathomechanisms underlining DRAM2-dependent cone-rod dystrophy, we generated iPSCs from two CORD21 patients and differentiated those to retinal organoids (ROs) and RPE cells." (PMID 38964324, 2024). "Another example is represented by two sisters, LL20 and LL253, both suffering from cone-rod dystrophy and found to carry a novel intronic variant, NM_001349884.2:c.517+5C>A, in DRAM2, which was prioritized based on a dbscSNV_ADA score of 0.66." (PMID 36909829, 2023). "Since human DRAM2 mutations cause cone-rod dystrophy, we investigated if cone photoreceptors were also affected in the mouse ko." (PMID 37691820, 2023). "We concluded that the DRAM2-associated retinopathy of our patients was a progressive rod-cone dystrophy, and the visual outcome was poor." (PMID 32079136, 2020). "Although DRAM2 mutations cause cone-rod dystrophy, Dram2 knockout mice show no overt degeneration or increased apoptosis." (PMID 41326361, 2025). "In addition to this early cone involvement followed by rod degeneration (i.e., cone-rod dystrophy), another aspect of DRAM2-retinopathy was identified in our mouse model." (PMID 37691820, 2023). "DRAM2-associated retinopathy has been reported as CORD21, i.e., cone-rod dystrophy." (PMID 32079136, 2020).
retinal degeneration (4 papers, 2020 to 2024). Degeneration of the retina. "To date, only one published study has investigated the function of DRAM2 in the context of retinal degeneration, showing significant loss of cone photoreceptors in Dram2 knockout mice from 4 months of age." (PMID 38964324, 2024). "Therefore, the variants in DRAM2 in Patients 1 and 2 were most likely responsible for retinal degeneration." (PMID 32079136, 2020). "In summary, our study provides novel insights into the cellular effects of DRAM2 deficiency in photoreceptors and RPE cells, contributing to our understanding of biological mechanisms underlying retinal degeneration." (PMID 38964324, 2024). "In conclusion, although no transcriptional changes were detected at 12 months, Dram2 loss causes a mild age-related retinal degeneration starting at 18 months, which is restricted to photoreceptor cells and not severe enough to affect vision in mice even at 21 months." (PMID 37691820, 2023). "A recent study using a Dram2 knockout mouse model has shown age-related retinal degeneration but no visual dysfunction in relatively old mice." (PMID 38964324, 2024). "Although DRAM2 localizes to the lysosomes of photoreceptor and retinal pigment epithelium (RPE) cells, its specific role in retinal degeneration has not been fully elucidated." (PMID 38964324, 2024).
retinal disease (3 papers, 2016 to 2023). "Three homozygous DRAM2 variants were identified by WES with target analysis of retinal disease-associated genes, viz., c.707_709dup, p.Arg236_Val237insGly in one family (Jikei-176); c.221G>A, p.Arg74His in one family (Kinki-12); and c.8_10delGGT, p.Trp3del in one family (Kinki-69)." (PMID 32079136, 2020). "No other variants of retinal disease-associated genes were detected in these 1314 families except for DRAM2 and EYS variants with high allele frequency (HAF) in a biallelic state." (PMID 32079136, 2020). "To further investigate DRAM2 expression at the cell type level, we leveraged single-nucleus RNA sequencing (scNucSeq) data from 4 donor eyes with no retinal disease diagnosis." (PMID 37691820, 2023).
Hodgkins lymphoma (2 papers, 2019 to 2021). A heterogeneous group of malignant lymphoid neoplasms of B-cell origin characterized histologically by the presence of Hodgkin and Reed-Sternberg (HRS) cells in the vast majority of cases. "ERβ-induced damage regulated autophagy modulator 2 (DRAM2)-mediated autophagy has been associated with a reduction of cancer cell proliferation in Hodgkin lymphoma (HL) cells." (PMID 31412908, 2019). "In addition, at least in vitro, ERβ-induced damage regulated autophagy modulator 2 (DRAM2)-mediated autophagy has been associated with a reduction in cancer cell proliferation in Hodgkin lymphoma (HL) cells." (PMID 34209162, 2021).
non-small cell lung carcinoma (2 papers, 2019 to 2020). A group of at least three distinct histological types of lung cancer, including non-small cell squamous cell carcinoma, adenocarcinoma, and large cell carcinoma.
age (1 paper, 2023). A temporal measurement of the time period elapsed since an identifiable point in the life cycle of an organism. "Furthermore, we observed that DRAM2 loss in human retinal pigment epithelial (RPE) cells resulted in increased susceptibility to stress-induced cell death in vitro and that Dram2 loss in mice caused age-related photoreceptor degeneration." (PMID 37691820, 2023).
age-related macular degeneration (1 paper, 2023). Age-related loss of vision in the central portion of the retina (macula), secondary to retinal degeneration. "We found that DRAM2 is ubiquitously expressed in the human eye and expression changes were observed in eyes with more common maculopathy such as Age-related Macular Degeneration (AMD)." (PMID 37691820, 2023). "To know if DRAM2 could also be involved in more common maculopathies, such as Age-related Macular Degeneration (AMD), we investigated whether DRAM2 expression level in the eye was altered in AMD patients." (PMID 37691820, 2023).
cone dystrophy (1 paper, 2022). An inherited ocular disorder characterized by the loss of cone cells, the photoreceptors responsible for both central and color vision. "Either cone–rod or rod–cone dystrophy phenotype is observed on electroretinography, reflecting the importance of DRAM2 in both photoreceptor types." (PMID 35806404, 2022).
esophageal adenocarcinoma (1 paper, 2020). A malignant tumor with glandular differentiation arising predominantly from Barrett mucosa in the lower third of the esophagus. "The statistically higher expressions of PLAUR, BIK, DRAM2, RNF41, STK38, ATG5, and PARP1 were measured in esophageal cancer than those in normal tissue, while statistically significant differences were also detected between ESCC and esophageal adenocarcinoma (EAC)." (PMID 32974198, 2020).
lung carcinoma (1 paper, 2019). "Next, to investigate whether DRAM2 expression was associated with the progression of NSCLC, we analyzed the correlation of DRAM2 expression with the clinicopathological characteristics of the lung cancer patients based on the immunohistochemical staining data." (PMID 30755245, 2019).
lymph node metastasis (1 paper, 2019). "Based on the result that DRAM2 correlated with lymph node metastasis, we first explored the effects of DRAM2 on cell migration of NSCLC, via transwell migration experiment, and the difference in transwell migration was statistically significant." (PMID 30755245, 2019). "Collectively, these observations indicate that the DRAM2 was overexpressed in NSCLC compared with the adjacent normal lung tissues, and its overexpression was associated with TNM stages and lymph node metastasis of NSCLC patients." (PMID 30755245, 2019). "Moreover we discovered that the expression of DRAM2 related with TNM stage and lymph node metastasis." (PMID 30755245, 2019).
memory impairment (1 paper, 2020). "The Morris water maze test revealed that overexpression of Dram2 significantly reversed the improvement effects of circLrp1b knockdown in TBI-induced spatial learning and memory impairment." (PMID 33147167, 2020).
myocardial ischemia (1 paper, 2022). A disorder of cardiac function caused by insufficient blood flow to the muscle tissue of the heart. "During acute myocardial ischemia, autophagy has been shown to confer cardioprotection, as deletions/mutations of proteins involved in the formation of the autolysosome (DRAM2, Ulk1, Atg7) either induce baseline cardiac dysfunction, or exacerbate MI pathophysiology." (PMID 35614179, 2022).
ovarian tumors (1 paper, 2017). "It is already known that DRAM2 is down-regulated in ovarian tumors and reduced expression of DRAM2 may contribute to anti-apoptosis in tumor cells." (PMID 28410234, 2017).
squamous carcinoma (1 paper, 2019). "According to established principles for evaluating immunostaining, the expression of DRAM2 was negative in the normal alveolar, and negative or very weakly positive in the normal bronchi, but relatively higher in squamous carcinoma tissues and adenomatous carcinoma tissues." (PMID 30755245, 2019). "Considering the expression of DRAM2 did not correlate with histology, we chose to upregulate and silence DRAM2 expression in A549 (adenocarcinoma) and SK-MEM-1 (squamous carcinoma, hereinafter referred to as SK) for subsequent experiments." (PMID 30755245, 2019).
ST Elevation Myocardial Infarction (1 paper, 2019). A myocardial infarction that produces elevation in the ST segments of the ECG. "Furthermore, it was demonstrated that genetic variants on chromosome 1p13.3 near the damage-regulated autophagy modulator 2 (DRAM2) gene were associated with non-ST elevation myocardial infarction in a case–control study." (PMID 31214022, 2019).
tumor (6 papers, 2017 to 2025). "Altogether these results suggest that targeting ERβ with selective agonists might affect HL cell proliferation and tumor growth via a mechanism that brings into play DRAM2-dependent autophagic cascade." (PMID 28052027, 2017). "DRAM2, another key factor in the fusion of autophagosomes and lysosomes, exhibited upregulated expression, further confirming that autophagic flux is blocked during combination therapy, leading to the disruption of the tumor cell’s autophagy-mediated protective mechanism." (PMID 40649969, 2025). "DRAM2 was preferentially upregulated in NSCLC tissues and higher expression of DRAM2 in NSCLC correlated with tumor node metastases stage and lymph node metastasis." (PMID 30755245, 2019). "However, the role of DRAM2 in the progression of human neoplasms is still unknown." (PMID 30755245, 2019). "DRAM2 overexpression was associated with tumor node metastases (TNM) stages (p = 0.025) and lymph node metastasis (p = 0.035), but did not correlate with age, biological sex, histology, or tumor differentiation (p > 0.05)." (PMID 30755245, 2019). "To confirm DRAM2 was overexpressed in tumor tissue, we analyzed DRAM2 mRNA expression in 20 pairs of fresh NSCLC samples via RT-PCR and 15 pairs of tissue specimens, which corresponded to RT-PCR to analyze DRAM2 expression through western blotting, and obtained the same results." (PMID 30755245, 2019).
cancer (3 papers, 2019 to 2021). A tumor composed of atypical neoplastic, often pleomorphic cells that invade other tissues. "It has been shown to suppress cell apoptosis and promote cancer cell proliferation via interaction with one of its putative target genes, DNA damage regulated autophagy modulator 2 (DRAM2)." (PMID 31798638, 2019). "Studies have confirmed that DRAM2 is downregulated in various cancer types, indicating that it may be part of the tumor signalling process." (PMID 31798638, 2019). "With the exception of serving as an autophagy-related protein in a few types of tumors, the protein DRAM2 had not been thoroughly studied in the context of cancer." (PMID 30755245, 2019).
retinopathy (3 papers, 2020 to 2023). "By assessing the different phenotypes resulting from DRAM2 loss in these various systems, our ultimate goal was to gain insights on DRAM2-retinopathy pathophysiology and understand the limitations of these different systems better." (PMID 37691820, 2023). "Including this report, 19 unique variants in DRAM2 associated with retinopathy caused were identified." (PMID 35806404, 2022). "The search in the previously published cases of retinopathy caused by biallelic variants in DRAM2 identified 6 reports with overall 24 cases from 14 families." (PMID 35806404, 2022). "We conclude from these findings and our findings that DRAM2-associated retinopathy exhibits not only cone-rod dysfunction but also rod-cone dysfunction." (PMID 32079136, 2020). "Patient 1153 was excluded from this report because her retinopathy was possibly affected by both the DRAM2 and EYS variants." (PMID 32079136, 2020). "Another patient with DRAM2-associated retinopathy had dark-adaptation difficulties that started in her third decade of life (rod dysfunction)." (PMID 32079136, 2020). "Hydroxychloroquine, an autophagy inhibitor, can be associated with similar retinopathy as DRAM2-associated retinopathy." (PMID 32079136, 2020). "This study aimed to determine the clinical course of three patients with DRAM2-associated retinopathy at an advanced stage of the retinopathy and to present the effects of the DRAM2 variants on the peripheral lymphocytes, determined by transmission electron microscopy (TEM)." (PMID 32079136, 2020). "Therefore in Patient 3, the DRAM2 variant, p.Trp3del, was considered to be responsible for her retinopathy." (PMID 32079136, 2020). "The pattern of visual-field-defect progression may be a characteristic of DRAM2-associated retinopathy." (PMID 32079136, 2020). "We used a combination of different systems and models to be able to uncover different aspects of DRAM2-retinopathy pathophysiology." (PMID 37691820, 2023). "Although the different cell specific effects we uncovered are consistent with DRAM2-retinopathy and AMD clinical presentation, the exact cellular mechanisms are still unclear." (PMID 37691820, 2023). "Leveraging results obtained with the different systems, we were able to recapitulate the pathognomonic clinical features of DRAM2-retinopathy." (PMID 37691820, 2023). "To gain insights into pathogenicity of DRAM2-related retinopathy, we used a combination of in vitro and in vivo models." (PMID 37691820, 2023). "Her older sister, who had similar and more severe retinopathy than that in Patient 3 (1159), had a homozygous EYS variant (p.Gly843Glu) in addition to the homozygous DRAM2 variant (p.Trp3del)." (PMID 32079136, 2020). "Overall, we concluded that the phenotypes of Patients 1, 2, and 3 to be pure DRAM2-associsted retinopathy." (PMID 32079136, 2020). "DRAM2-retinopathy is a slow progressive disease and chronic models would be more appropriate." (PMID 37691820, 2023). "Alternatively, patients with systemic dysfunction suffered by DRAM2 malfunction may possibly be unable to survive until the retinopathy is expressed." (PMID 32079136, 2020). "Electron microscopic findings of the photoreceptors and RPE cells have never been reported in patients with DRAM2-associated retinopathy." (PMID 32079136, 2020). "The findings at the advanced stage of DRAM2-associated retinopathy have not been reported, and a single retinal involvement by a mutation of the DRAM2 gene is unexplained." (PMID 32079136, 2020).
DRAM2 also shares sentences with these, for which no sentence is quoted: achromatopsia (1 paper); adenocarcinoma (1); autosomal recessive cone rod dystrophy (1); bacterial infection (1); breast carcinoma (1); esophageal cancer (1); injury (1); macular degeneration (1); Macular dystrophy (1); Non-ST Elevation Myocardial Infarction (1); Photophobia (1); retinoblastoma (1); virus infection (1).